MIR548AG1 (microRNA 548ag-1)
Synonyms: hsa-mir-548ag-1
Gene: MicroRNA gene on chromosome 4 (60,922,619 to 60,922,684, forward strand). Ensembl gene ENSG00000265829.
Homologues: Orthologues: chimpanzee MIR548AG1 (100% identical). Paralogues in human: MIR548O2 (82% identical), MIR548AN (80% identical), MIR548AZ (80% identical), MIR548Z (80% identical), MIR548AY (79% identical), MIR548H3 (79% identical), MIR548AG2 (77% identical), MIR548AH (77% identical), MIR548AA1 (76% identical), MIR548AJ1 (76% identical), MIR548X2 (76% identical), MIR548AX (74% identical), and 13 more.